ASB11 (ankyrin repeat and SOCS box containing 11)
Description:
Substrate-recognition component of a cullin-5-RING E3 ubiquitin-protein ligase complex (ECS complex, also named CRL5 complex), which mediates the ubiquitination and subsequent proteasomal degradation of target proteins, such as BIK, DIRAS2 and RPN1. The ECS(ASB11) complex acts as a regulator of the endoplasmic reticulum unfolded protein response by mediating ubiquitination and degradation of BIK.
Synonyms: DKFZp779E2460
Tractability: No criterion of Open Targets' tractability assessment is met for any kind of drug.
Gene: Protein-coding gene on chromosome X (15,281,697 to 15,315,640, reverse strand). Ensembl gene ENSG00000165192.
Subcellular location: Endoplasmic reticulum
Pathways (Reactome):
Immune System: Antigen processing: Ubiquitination & Proteasome degradation
Metabolism of proteins: Neddylation
Gene Ontology:
Molecular function: ubiquitin-like ligase-substrate adaptor activity
Biological process: endoplasmic reticulum unfolded protein response; proteasome-mediated ubiquitin-dependent protein catabolic process; protein K11-linked ubiquitination; protein ubiquitination; positive regulation of protein catabolic process; intracellular signal transduction
Cellular component: Cul5-RING ubiquitin ligase complex; endoplasmic reticulum; cytosol
Homologues: Orthologues: chimpanzee ASB11 (99% identical), rabbit ASB11 (97% identical), guinea pig ASB11 (96% identical), pig ASB11 (93% identical), mouse Asb11 (91% identical), rat Asb11 (91% identical), dog ASB11 (81% identical), macaque ASB11 (76% identical), tropical clawed frog asb11 (67% identical). Paralogues in human: ASB5 (54% identical), ASB9 (46% identical).
Diseases named in the same sentence as ASB11 in open-access papers:
ASB11 is named in the same sentence as 4 diseases in open-access papers, as found by Europe PMC text mining. Sharing a sentence is not in itself a finding about the gene and the disease. The quoted sentences say what the papers report.
coronary heart disease (1 paper, 2015). "We examined the plasma Rnf207, Fbxo32, Trim54, Trim63, Kbtbd10 and Asb11 in three groups (the AMI, coronary heart disease (CHD) and healthy groups)." (PMID 25599194, 2015).
melanoma (1 paper, 2021). A malignant, usually aggressive tumor composed of atypical, neoplastic melanocytes. "Additionally, our study identified genes without reported expression in CMM and nevi or biological function related to melanoma progression, including CCL3L3, NPY1R, IL11A, FCGR1B, OAS2, ASB11, FCGR3A, and GLA." (PMID 35008167, 2021).
cancer (1 paper, 2025). A tumor composed of atypical neoplastic, often pleomorphic cells that invade other tissues. "Overall, targeting ASB11 and its associated degradation pathway may represent a novel and effective therapeutic approach for various cancers, including breast, colon, lung, and ovarian cancers, particularly in settings where traditional treatments are less effective due to drug resistance." (PMID 40841912, 2025). "This combined treatment demonstrated a potent reduction in tumor growth, an effect not achieved with either treatment alone, underscoring the potential of ASB11 inhibition as an adjunct to Bik-based cancer therapies." (PMID 40841912, 2025). "Blocking the ASB11-dependent degradation of BikDD increases its stability, effectively sensitizing cancer cells to pro-apoptotic stimuli." (PMID 40841912, 2025). "Disrupting this degradation pathway by either inhibiting ASB11 or knocking down Cul5 stabilizes Bik, which has been shown to increase cell apoptosis, supporting a therapeutic angle for cancer treatments where enhanced Bik stability may be desirable." (PMID 40841912, 2025). "Bik stabilization by blocking ASB11-mediated degradation appears to amplify Bik’s apoptotic activity, suggesting that modulating this pathway could enhance responses to cancer treatments in TNBC and potentially in other cancer types." (PMID 40841912, 2025).
ASB11 also shares sentences with these, for which no sentence is quoted: autoimmune diseases of the thyroid (1 paper).